ALK (ALK receptor tyrosine kinase)
Diseases named in the same sentence as ALK in open-access papers (continued):
Sharing a sentence is not in itself a finding about the gene and the disease.
neuroblastoma (continued). "Comprehensive research has delineated intricate molecular pathways involving diverse ALK isoforms, mutations, and regulatory mechanisms, particularly emphasizing their implications in neuroblastoma development and potential therapeutic strategies." (PMID 38397899, 2024). "Overall, our data suggests that combined use of ALK TKIs and FTIs, constitutes a therapeutic approach to treat high risk neuroblastoma although prolonged therapy is likely required to prevent relapse." (PMID 38653965, 2024). "For example, neuroblastoma cells harboring anaplastic lymphoma kinase (ALK) mutations experienced growth inhibition in experimental models following ALK silencing by RNAi." (PMID 38836106, 2024). "Genetic alterations of ALK are associated with unfavorable prognosis when present at diagnosis and are identified in 20% to 43% of patients with relapsed or refractory neuroblastoma." (PMID 39177282, 2024). "On the other hand, the third-generation ALK TKI lorlatinib is highly effective against a wide range of ALK mutant variants expressed in neuroblastoma." (PMID 39177282, 2024). "Since expression of FN1 has been linked to the mesenchymal state of neuroblastoma, we analyzed the transcriptome of the human stem cell-derived ALK/MYCN tumors." (PMID 38451815, 2024). "Several studies have demonstrated that activated ALK is an oncogenic driver in neuroblastoma, especially when associated with MYCN amplification." (PMID 38877641, 2024). "ALK amplification is another set of somatic mutations, accounting for ~14% of high-risk neuroblastomas." (PMID 38391759, 2024). "We describe the effect of single-agent lorlatinib in five patients with ALK-mutated relapsed or refractory metastatic high-risk neuroblastoma." (PMID 39177282, 2024). "Targeting and silencing ALK oncogenic mutations with this method also significantly reduced tumor progression in neuroblastoma models." (PMID 38836106, 2024). "Relapsed neuroblastoma exhibiting both ALK mutation and MYCN amplification is regarded as a clinically challenging high-risk patient group with low survival rates." (PMID 38858548, 2024). "Gain-of-function point mutations in ALK are associated with neuroblastoma and most often occur in the kinase domain, with 85% of all ALK point mutations seen at either F1174 or R1275." (PMID 38231572, 2024). "In conclusion, a complex interplay of genetic changes, such as MYCN amplification, segmental chromosomal modifications, gene expression profiles, ALK mutations, and other genomic variants, contributes to the complex pathogenesis of neuroblastoma." (PMID 39612452, 2024). "Studies identified specific mutations at F1174 and R1275 in neuroblastoma tumor cells that activate ALK, establishing its role in the disease." (PMID 38397899, 2024). "Several of these targeted agents have shown efficacy in pediatric cancers, as in the use of ALK inhibitors such as crizotinib in ALK-mutated neuroblastoma (NB) and CDK4/6 inhibitors including Palbociclib in pediatric sarcomas." (PMID 38347552, 2024). "As the most frequently mutated gene in neuroblastoma, ALK aberrations contribute to tumor growth, proliferation, and migration by activating tyrosine kinase receptors." (PMID 39338204, 2024). "Chloe, who works closely with Karen Liu's research team, has developed a cell line harbouring a mutation in ALK gene, that recapitulates a human mutation that has been found in patients with neuroblastoma." (PMID 38874999, 2024). "All five patients with relapsed or refractory ALK mutation-positive neuroblastoma who have received lorlatinib monotherapy in Sweden so far were included in the study." (PMID 39177282, 2024). "ALK-activating mutations have been detected in most familial and in 10% of sporadic neuroblastoma cases." (PMID 38666930, 2024). "In another study examining ALK 117T1 mutation in neuroblastoma, an association was found between the mutation and ligand-independent activation in ALK, causing an increase in neurite growth and downstream signaling." (PMID 38835344, 2024).
neuroblastoma (continued). "Mechanistically, in ALK-mutated neuroblastoma cells, both ALK and IGF1R contribute significantly to the activation of the downstream PI3K-AKT and RAS-MAPK signaling pathways." (PMID 37686528, 2023). "The identification of ALK mutations in subsets of neuroblastoma primary tumors and more commonly in relapsed samples resulted in trials of ALK inhibitors and development of newer compounds with better efficacy against activating missense mutations." (PMID 38032104, 2023). "The most frequent mutations that lead to activation of the RAS/MAPK pathway in neuroblastoma affect the gene that encodes for anaplastic lymphoma kinase (ALK)." (PMID 36807339, 2023). "Intriguingly, the third-generation TKI that targets both ALK and ROS1, lorlatinib, has recently shown promise in patients with ALK mutated neuroblastoma, but most of the studies are still at phase I clinical trial." (PMID 36900212, 2023). "It shares around 80% of similarity in kinase domain with ALK (anaplastic lymphoma kinase) which is mutated in many human cancers like lymphomas and neuroblastomas." (PMID 37287033, 2023). "Autosomal dominant gain-of-function ALK mutations are reported in about 50% of familial neuroblastoma cases." (PMID 36807339, 2023). "While ALK mutation is the most common somatic mutation in neuroblastoma, crizotinib was compromised due to the interference by common ALK mutation F1174." (PMID 36900212, 2023). "All common neuroblastoma ALK hotspot mutations were represented in tumor sequencing results for eligibility, including F1174C/L (51%), R1275Q (33%) and F1245Y/L (12%), one ALK amplification and one pathologic D1276_R1279 ALK-activating mutation." (PMID 37012551, 2023). "In this study, our results provide evidence for the use of SHP2 in combination with ALK-TKIs in high-risk and/or relapsed neuroblastoma tumors harboring ALK mutations." (PMID 38032104, 2023). "Activating point mutations in Anaplastic Lymphoma Kinase (ALK) have positioned ALK as the only mutated oncogene tractable for targeted therapy in neuroblastoma." (PMID 37147298, 2023). "ALK mutations are among the leading cause of hereditary neuroblastoma and account for more than 14% of the somatically acquired alterations." (PMID 37765276, 2023). "Here, we show that RAS-MAPK pathway activation through RAS mutation, NF1 deletion or ALK mutation also has a destabilizing effect in neuroblastoma." (PMID 36895472, 2023). "The ORR was ~75% (6/8) and 70% (7/10) among ALCL and IMT patients that harbor ALK rearrangements, respectively but it was only around 20% (6/30) in neuroblastoma (which usually harbors mutations in ALK)." (PMID 37773318, 2023). "Some ALK mutations have also been identified in neuroblastomas and can either be germline or somatic." (PMID 37773318, 2023). "In a clinical case study of a relapsed, metastatic ALK F1174L-mutated neuroblastoma patient, there was a complete response to lorlatinib initially that relapsed after 13 months, associating with development of an activating N-Ras Q61K mutation." (PMID 37414143, 2023). "ALK F1174L mutated neuroblastoma is thought to be an aggressive disease phenotype, which confers resistance to crizotinib." (PMID 37773318, 2023). "Patients ≥12 months with measurable or evaluable refractory or relapsed high-risk neuroblastoma, including CNS metastases and/or prior treatment with ALK TKIs aside from lorlatinib, were eligible." (PMID 37012551, 2023). "The New Approaches to Neuroblastoma Therapy Consortium (NANT) is conducting a phase 1 study of lorlatinib for children with ALK-mutated refractory or relapsed neuroblastoma (NCT03107988)." (PMID 37835416, 2023). "For instance, ALK point mutations were permitted in some studies, and mutations such as F1174L (common ALK‐activating mutations seen in neuroblastoma) have been shown to confer resistance to crizotinib in neuroblastoma and other cancers." (PMID 37773318, 2023).
neuroblastoma (continued). "In neuroblastoma at diagnosis, ALK mutations or amplifications are detected in 14% of high-risk tumors and their presence is associated with unfavorable outcomes." (PMID 38032104, 2023). "The ALK kinase domain hotspot mutation F1174 (mutated to C, I, L, S, or V) is found in around 85% of cases involving ALK mutations in neuroblastoma." (PMID 38274094, 2023). "We found an overall ALK mutation frequency of 10.5% in a large and representative cohort of neuroblastomas obtained at diagnosis, which is largely in the range of ALK mutation frequencies reported previously." (PMID 36807339, 2023). "Gain-of-function mutations within the ALK kinase domain—F1174, F1245, and R1275—represent around 85% of ALK mutations in neuroblastoma." (PMID 37765276, 2023). "ALK aberrations (mutations or amplifications) are present in most cases of hereditary neuroblastoma and in 10–15% of sporadic cases." (PMID 37835416, 2023). "For neuroblastoma patients with ALK F1245 or R1275 hotspot mutations, genomic distance precludes assignment of secondary mutations as cis versus trans based on our sequencing reads." (PMID 37147298, 2023). "Single-agent lorlatinib demonstrated clinical activity across patients of all ages harboring the three neuroblastoma-specific hotspot ALK mutations, including patients who had previously received other ALK TKIs." (PMID 37012551, 2023). "Most patients <18 years of age with MYCN-amplified/ALK-mutated neuroblastoma (6/7, 86%) had PD before or by the end of course 2, whereas one patient had MR." (PMID 37012551, 2023). "Some mutations in ALK cause its aberrant activation, which is related to the development of neuroblastoma, a tumor originating from multipotent cells of the neural crest." (PMID 37443767, 2023). "We modeled in cis ALK compound mutations in human neuroblastoma-derived cell lines to assess their effects on lorlatinib pharmacodynamics." (PMID 37147298, 2023). "It is known that the amplification of the MYCN oncogene and activating mutations of the ALK oncogene can transform progenitor cells of the sympathoadrenal lineage to generate neuroblastoma." (PMID 37046647, 2023). "Our results provide insight into acquired lorlatinib resistance mutations in patients with ALK-driven relapsed/refractory neuroblastoma." (PMID 37147298, 2023). "Only few studies with limited patient numbers have reported on ALK mutation and amplification frequencies in relapsed or progressive neuroblastoma, despite their potential relevance as therapeutic targets for these patients with poor survival expectations." (PMID 36807339, 2023). "Around ~1–2% of neuroblastoma cases are inherited (autosomal dominant) and ~50% of them have germline gain-of-function ALK mutation." (PMID 37773318, 2023). "ALK mutations are found in around 10-15% of sporadic neuroblastomas but are also typically responsible for familial forms." (PMID 37213274, 2023). "The finding that intermediate-risk neuroblastomas of young stage 4 patients at diagnosis harbor ALK mutations at high frequencies provides a starting point for targeted treatment of these children." (PMID 36807339, 2023). "Surprisingly, ALK inhibition by lorlatinib, when administered as a single agent in neuroblastoma patients, caused weight gain and hypertriglyceridemia, an effect observed also in NSCLC patients, but not with other ALK inhibitors such as ceritinib." (PMID 37414143, 2023). "Similar to other studies, ALK amplification occurred exclusively in MYCN-amplified neuroblastomas and were mutually exclusive with ALK point mutations." (PMID 36807339, 2023). "The majority of ALK-altered neuroblastoma are associated with sporadically acquired somatic mutations." (PMID 37773318, 2023). "Aberrant activation of the anaplastic lymphoma kinase (ALK) RTK by activating point mutations or amplification is identified in 5–12% of neuroblastomas." (PMID 37686528, 2023).
neuroblastoma (continued). "Here, we also show that SHP2 inhibitors can be effectively combined with ALK inhibitors in targeting ALK-mutated neuroblastoma, including those with acquired resistance to ALK-TKI therapies." (PMID 38032104, 2023). "We therefore suggest to evaluate the therapeutic benefit of ALK inhibitors in intermediate-risk patients with ALK-mutated neuroblastoma in prospective clinical trials." (PMID 36807339, 2023). "Using ALK-driven neuroblastoma cell lines, we show that ALK-mutated cells are more sensitive to IGF1R inhibition than ALK-amplified cells, and a synergistic effect is obtained when combining ALK and IGF1R inhibitors." (PMID 37686528, 2023). "Given the propensity of ALK-mutated neuroblastoma to develop ALK resistance, maintaining a pipeline of ALK inhibitors with the ability to overcome this resistance remains an important area of research." (PMID 37835416, 2023). "Among neuroblastoma cases, response to ceritinib were observed in cases carrying ALK p.Arg1275 mutations." (PMID 37773318, 2023). "Our results show that combining TNO155 with ALK inhibitors currently in clinical use reduces tumor growth in neuroblastoma cell lines, zebrafish, and murine models harboring ALK mutations." (PMID 38032104, 2023). "Patient 3 treated at DL1 on cohort A1 had a germline ALK R1275Q mutation with metastatic primary refractory neuroblastoma." (PMID 37012551, 2023). "Less is known about the impact of ALK mutations on the CRC in neuroblastoma, but most available neuroblastoma cell lines that harbor activating ALK mutations, such as Kelly and SY5Y, rely on the adrenergic CRC." (PMID 37183825, 2023). "MYC, ALK, and Augα are all located on the 2p chromosome, and the exact 2p gain region is associated with the development of neuroblastoma." (PMID 37892172, 2023). "Because lorlatinib has broader efficacy against common neuroblastoma ALK-mutated proteins and is now included in frontline neuroblastoma trials, we next assessed the efficacy of combining TNO155 with lorlatinib." (PMID 38032104, 2023). "Although neuroblastoma is strongly associated with altered ALK signaling, ALK gain-of-function mice develop sympathetic ganglia hyperplasia and not cancer, and additional key triggers are necessary for cancer development, typically MYC amplification." (PMID 37892172, 2023). "Drug interactions between TNO155 and ceritinib were assessed using the EOB model, and EOB scores > 0 (indicating synergy for this methodology) were exclusively observed for neuroblastoma cell lines harboring ALK mutations." (PMID 38032104, 2023). "In neuroblastoma, ALK mutations are mostly activating missense single nucleotide variants (SNV) leading to increased kinase activity by disrupting the auto-inhibited conformation of the kinase, thereby promoting tumor growth, proliferation, and migration." (PMID 36807339, 2023). "The most notable existing targeted therapies for high-risk neuroblastoma thus far are ALK inhibitors and anti-GD2 therapies, both of which have become mainstays of treatment both in the upfront and relapsed settings." (PMID 37835416, 2023). "Patient P13 was particularly informative for analyzing the clonal evolution of ALK mutations in neuroblastoma, as tumor material of six different timepoints was available for monitoring allelic fractions over the course of disease by ddPCR." (PMID 36807339, 2023). "Integration of a potent targeted therapy in the treatment of newly diagnosed patients with ALK-aberrant, high-risk neuroblastoma holds substantial promise for improving patient outcomes." (PMID 37012551, 2023). "The RP2D of 115 mg/m2 daily in patients <18 years of age was about twice the regulatory-approved adult NSCLC starting dose, as predicted by pre-clinical studies of neuroblastoma harboring ALK mutations." (PMID 37012551, 2023). "In a previous study of 54 paired neuroblastoma samples, an increase of the ALK mutation frequency from 16.7% at diagnosis to 25.9% at relapse has been reported." (PMID 36807339, 2023).
neuroblastoma (continued). "For example, ALK point mutations and amplifications are common in neuroblastoma, whereas ALK fusions/rearrangements are more common in IMT and ALCL, but all of these tumor types can present with ALK overexpression." (PMID 37773318, 2023). "ALK amplification is also observed in approximately 15% of MYCN-amplified primary neuroblastomas, associating with worsened clinical outcomes." (PMID 37414143, 2023). "Lorlatinib induced complete tumor regression in both crizotinib-resistant and sensitive neuroblastoma-derived xenografts harboring F1174L, F1245C or R1275Q ALK mutations, demonstrating lorlatinib’s potential to overcome crizotinib resistance." (PMID 37012551, 2023). "The incidence of ALK point mutations is low, and their oncogenic role has been found only in neuroblastoma." (PMID 36591504, 2022). "There are three hot-spot residues within the ALK kinase domain (F1174, F1245 and R1275) where most ALK mutations are found in neuroblastoma patients." (PMID 36140661, 2022). "ALK is often overexpressed or constitutively activated by gain-of-function mutations in neuroblastoma, and ALK inhibitors have been tested in clinical trial for neuroblastoma treatment." (PMID 36585695, 2022). "One neuroblastoma study reported loss of two different relapse‐specific hotspot ALK mutations in a patient following crizotinib treatment." (PMID 36029175, 2022). "Against neuroblastoma, only one drug, ceritinib (an ALK inhibitor), had satisfactory effect, causing a decrease of 30% in the tumor size." (PMID 36142160, 2022). "This novel observation due to intra‐tumoral spatial and temporal heterogeneity emphasizes the importance of confirming the continued presence an ALK mutation at relapse prior to the use of ALK inhibitors in relapsed/refractory neuroblastoma." (PMID 36029175, 2022). "In line with our results, an independent report suggested NF1 alterations were potentially involved in ALK resistance and a case report described a de novo NRASQ61K mutation upon development of ALK inhibitor resistance in a lorlatinib-treated neuroblastoma." (PMID 35689207, 2022). "We identified MEK inhibitor sensitivity as a collateral sensitivity of ALK inhibitor resistance due to NF1 loss in ALK-mutated neuroblastoma cells." (PMID 35689207, 2022). "Few somatic mutations are associated with neuroblastoma other than ALK (anaplastic lymphoma kinase) found in 8-10% of neuroblastoma cases." (PMID 36185250, 2022). "The ALK (anaplastic lymphoma kinase) gene harbors the most frequently detected somatic mutations in neuroblastoma, found in 8–10% of neuroblastoma cases." (PMID 35362827, 2022). "Although the loss of a hotspot ALK mutation at relapse is rare, here we report two cases and a set of paired immortalized neuroblastoma cell lines." (PMID 36029175, 2022). "ALK detection methods including Sanger sequencing, targeted next‐generation sequencing and a new ALK Agena MassARRAY technique were used to detect common hotspot ALK variants in tumors at diagnosis and relapse from two high‐risk neuroblastoma patients." (PMID 36029175, 2022). "Activating mutations for ALK are found in 6–10% of spontaneous cases and in almost 50% cases of familial neuroblastoma (1–2% of total neuroblastoma cases)." (PMID 34716856, 2022). "In this first focused description of the mutational landscape of neuroblastoma in an Asian population, prevalence of mutations resembled Western series, most commonly involving genes such as ALK and ATRX." (PMID 35768791, 2022). "Neuroblastoma, a childhood tumor originating from the sympathetic nervous system, is a prototypical example of a cancer with recurrent ALK mutations." (PMID 35689207, 2022). "Mutations of ALK are also present in familial neuroblastomas which encompass 1–2% of the neuroblastoma patients." (PMID 35362827, 2022). "The application of several ALK inhibitors in treating high-risk neuroblastoma patients is under development in clinical trials." (PMID 36585695, 2022).